LIPG (lipase G, endothelial type)
Diseases named in the same sentence as LIPG in open-access papers (continued):
Sharing a sentence is not in itself a finding about the gene and the disease.
tumor (continued). "Xenograft studies also demonstrated that LIPG depletion completely inhibited the in vivo tumor development of MDA-MB-468 in nude mice." (PMID 29350614, 2018). "To confirm the central role of LIPG activity in BCa tumour growth, and given the overlapping phenotypes of cell growth impairment, we tested the capacity of LIPG and its catalytic activity to rescue FoxA depletion in tumour growth." (PMID 27045898, 2016). "Here we reveal that FoxA factors provide a central metabolic growth function by specifically regulating LIPG expression, thereby allowing the acquisition of indispensable extracellular lipids for BCa tumour proliferation." (PMID 27045898, 2016). "In vitro experiments suggested that LIPG suppression could inhibit the proliferation and migration of EC cells, indicating its role in tumor progression." (PMID 40426878, 2025). "All these observations indicate that LIPG is a key lipolytic enzyme involved in tumor cell OXPHOS." (PMID 35954428, 2022). "DANCR binds to LIPG, which enables tumor cells to maintain the expression." (PMID 35954428, 2022). "We therefore investigated if LIPG in tumor cells plays a key role in regulating FAO." (PMID 35954428, 2022). "Collectively, these results suggest that a direct interaction between LIPG and DANCR may impact LIPG expression in tumor cells." (PMID 35954428, 2022). "In summary, these results demonstrate that tumor cells require LIPG for mitochondrial OXPHOS." (PMID 35954428, 2022). "DANCR binds to LIPG, enabling tumor cells to maintain LIPG protein stability and OXPHOS." (PMID 35954428, 2022). "LIPG overexpression facilitates the uptake of PUFAs, thereby contributing to tumor cell survival." (PMID 35954428, 2022). "Thus, we decided to determine if LIPG participates in remodeling the chromatin structure during tumor cell lipid metabolism." (PMID 35954428, 2022). "Decreased H3K27ac peaks were observed within the HDAC6 locus in LIPG-depleted tumor cells." (PMID 35954428, 2022). "We previously reported that LIPG prominently expresses in TNBC for tumor metastasis." (PMID 35954428, 2022). "Our finding of DTX3L-dependent regulation of LIPG expression may have important implications to tumor-microenvironmental interactions occurring in TNBCs through secreted immune cytokines like IFNs." (PMID 29350614, 2018). "Normal breast epithelial cells showed a lower expression of LIPG than cells from tumour specimens." (PMID 27045898, 2016). "Furthermore, gene expression analysis confirmed FoxA depletion and LIPG expression in the tumour populations at the end point of the tumour growth experiment and the rescue was also confirmed in cell culture." (PMID 27045898, 2016). "LIPG may facilitate EC tumor cell growth by increasing lipid utilization." (PMID 40426878, 2025). "Thus, our finding revealed a new mechanism by which DANCR regulates LIPG expression in tumor cells." (PMID 35954428, 2022). "Thus, cynaroside could disrupt the interaction between LIPG and vimentin and subsequently reduced tumor cell invasion." (PMID 35954428, 2022). "Therefore, pitavastatin might have tumor suppressive effects by modulation of LIPG expression in CRC." (PMID 35108261, 2022). "Furthermore, blocking LIPG enzymatic activity may potentially promote CSC properties as well as EMT/basal-like features in tumor cells and induce the dormancy of DTCs." (PMID 32488004, 2020). "Similarly, LIPG-depleted cells were unable to grow tumours in vivo." (PMID 27045898, 2016). "Heatmap analysis showed marked upregulation of PLIN3, whereas LIPG, DGAT2, CIDEC, and PLIN1 were down-regulated in tumor tissues and GbPDTOs compared to those in normal tissues." (PMID 41376821, 2025). "Compared to adjacent normal tissues, tumor tissues exhibited significantly reduced expression of PTGIS, DGKB, HSD17B13, INMT, and ACACB, while PLA2G10, GRHL1, LIPG, and PLA2G4F were markedly upregulated." (PMID 40426878, 2025).
tumor (continued). "Their work indicated that cynaroside, a novel LIPG inhibitor, effectively suppresses DANCR expression in TNBC cells, significantly impeding tumour formation." (PMID 38877534, 2024). "Since high expression of LIPG is detected in CRC, it is possible to apply LIPG for a potential and auxiliary tumor biomarker and cancer gene therapy." (PMID 39069526, 2024). "Our study shows that ZDHHC1, acting as a tumor suppressor gene, inhibits the growth of CRC cells and downregulates the expression of LIPG through palmitoylation of IGF2BP1." (PMID 39069526, 2024). "In a similar line, we also observed increased expression of LIPG and corresponding lipase activity after silencing of ANGPTL4 in ECs, but in our case, we found reduced angiogenesis and tumor growth." (PMID 38086791, 2023). "Since OXPHOS is a critical metabolism pathway to maintain TNBC tumor growth, we decided to analyze long non-coding RNA DANCR, LIPG, and signature genes of OXPHOS in an RNA-seq database available from the Cancer Genome Atlas (TCGA)." (PMID 35954428, 2022). "Thus, we hypothesized that DANCR may impact LIPG protein expression in tumor cells." (PMID 35954428, 2022). "Towards this end, we discovered a natural compound, the LIPG inhibitor cynaroside, which efficiently suppressed LIPG enzyme activity as well as OXPHOS in TNBC cells, leading to impaired tumor formation in vivo." (PMID 35954428, 2022). "The present studies were aimed at determining how XEN445, a specific inhibitor targeting LIPG phospholipase activity, impacts on TNBC tumor formation and malignant features." (PMID 32488004, 2020). "Xenograft studies further demonstrated that similar to DTX3L knockdown, knockdown of either LIPG or ISG15 completely abolished the DTX3L overexpression-enhanced growth of MDA-MB-468 xenograft tumors and also significantly inhibited tumor development." (PMID 29350614, 2018). "However, to date, LIPG has not been linked to tumour growth." (PMID 27045898, 2016). "Recently, there is a renewed attention on LIPG, which accompanies tumor initiation and growth in TNBC; however, the mechanism of LIPG overexpression in tumor cells remains unclear." (PMID 35954428, 2022). "Therefore, more work is required to prove that LIPG mediates the inhibitory effect exerted by pitavastatin on CRC cell viability, and a feasible method would be patient-derived tumor xenograft (PDX) models." (PMID 35108261, 2022). "LIPG knockdown by siRANs or shRANs led to metabolic changes characterized by a reduction in mitochondrial OXPHOS and a concomitant increase in oleic acid uptake in tumor cells." (PMID 35954428, 2022). "Our study suggests that inhibition of LIPG phospholipase activity only impedes primary tumor growth as well as metastatic outgrowth and has no impact on dormant DTCs and quiescent primary tumor cells." (PMID 32488004, 2020). "Next, we showed that LIPG expression in primary tumours was specific to BCa tumour cells and not to other stroma cellular entities." (PMID 27045898, 2016). "Tumor tissue derived DNA treatment affected INSIG 1 and LIPG expression." (PMID 26133168, 2015). "Through a literature survey, we identified that GPX3, LDOC1, LXN, and UCHL1, but not LIPG, have been reported as tumor suppressor genes, and that their expression was mediated by promoter DNA methylation." (PMID 26317789, 2015). "Importantly, LIPG knockdown inhibits OXPHOS and TNBC tumor formation." (PMID 35954428, 2022). "Because of the same reason, i.e., that all our samples were collected before cancer diagnosis, it is not likely that tumor-secreted LIPG is responsible for high plasma LIPG levels, or that increased LIPG reflects tumor-induced increased inflammatory state in our patients." (PMID 34001944, 2021).
tumor (continued). "Further analysis showed that LIPG expression levels in primary tumours do not have the capacity to stratify patients for differential risk of overall or disease-free survival and are not dependent on estrogen signalling, thus reinforcing the notion that LIPG is essential for BCa growth." (PMID 27045898, 2016). "Found tumor foci were identified in the animal group injected with control scramble shRNA-expressing MDA-MB-468 cells, but not in the group injected with LIPG shRNA-expressing cells." (PMID 29350614, 2018). "Our study showed that LIPG can promote CRC proliferation by increasing intracellular lipid storage, which suggests that mechanisms of lipid metabolism may be conserved regardless of tumor location." (PMID 39069526, 2024).
cancer (15 papers, 2015 to 2025). A tumor composed of atypical neoplastic, often pleomorphic cells that invade other tissues. "LIPG is a gene encoding a phospholipase, which has been implicated in cancer development and progression." (PMID 39191281, 2024). "LIPG, which belongs to the TG lipase family and is associated with lipid metabolism, probably modulates the generation, development, and prognosis of cancers by regulating lipid metabolism." (PMID 39613907, 2024). "Furthermore, LIPG was identified as a key hub gene through the intersection of nine machine learning algorithms, demonstrating strong associations with both cancer progression and immune infiltration." (PMID 40426878, 2025). "We predict that the regulation of DTX3L-ISG15 signaling may be different between LIPG-proficient and LIPG-deficient cancer cells." (PMID 29350614, 2018). "Two of these genes, SLC34A2 and LIPG, are involved in cancer in humans and in hypoxic responses and ROS regulation in cancer cells." (PMID 39191281, 2024). "Our previous reports demonstrated that LIPG activates cancer stem cell self-renewal and promotes TNBC tumorigenesis in vivo." (PMID 35954428, 2022). "There are few studies on plasma levels of LIPG in cancer and other pathologies, and they are quite discordant, with mean values ranging from 0.05 to 420 ng/ml 40–45." (PMID 34001944, 2021). "To summarize, LIPG upregulation seems to be one of the mechanisms how cancer cells can guarantee fatty acid supply from extracellular sources under conditions where oxidative stress blocks endogenous synthesis." (PMID 34001944, 2021). "LIPG possesses a lipase-dependent function that supports cancer cell proliferation and a lipase-independent function that promotes invasiveness, stemness and basal/epithelial-mesenchymal transition features of TNBC." (PMID 29350614, 2018). "We did not found any data in the literature concerning the expression of LIPG in drug-resistant cancers or cancer cell lines." (PMID 28611294, 2017). "LIPG silencing significantly inhibited cancer cell proliferation." (PMID 39069526, 2024). "Additionally, transwell assays revealed that LIPG knockdown markedly impaired the invasion ability of cancer cells." (PMID 39069526, 2024). "Based on these findings, we speculated that targeting LIPG is a promising strategy in cancer therapy." (PMID 35954428, 2022). "Therefore, these two identified functional aspects of LIPG allow cancer cells to have more plasticity in regulating cell proliferation, stemness and EMT." (PMID 29350614, 2018). "Given that IFNs can induce DTX3L expression, IFNs may enhance LIPG expression in cancer cells through their stimulating effects on DTX3L expression." (PMID 29350614, 2018). "By querying the Oncomine Database, LIPG was shown to be highly expressed in CRC, as compared to other types of cancer." (PMID 35108261, 2022). "Furthermore, in the present study, overexpression of bta-miR-149-5p significantly (p < 0.05) upregulated LIPG (endothelial lipase) and KLF12 expression, which perform vital roles in cancer." (PMID 33922274, 2021). "By comparing this mutant line with parental and wild-type LIPG-expressing lines, we were able to examine both enzymatic and non-enzymatic effects of LIPG in cancer cells." (PMID 29350614, 2018). "It would be important in the future to reveal how cancer cells separately regulate enzymatic and non-enzymatic functions of LIPG during their tumorigenesis, metastasis and chemoresistance." (PMID 29350614, 2018). "On the other hand, several cancer genes, notably IGF2BP3, IGF2, and LIPG, do not produce chimeras but are consistently upregulated by geneUIB fusions." (PMID 32631391, 2020). "This natural design of dual functional roles for LIPG is necessary as cell proliferation is not always coupled with the EMT and active in cancer stem cells." (PMID 29350614, 2018).
cardiovascular disease (4 papers, 2014 to 2025). "Therefore, LIPG inhibitors have shown therapeutic potential for cardiovascular disease." (PMID 32488004, 2020).
infection (3 papers, 2023 to 2025). The state of being infected such as from the introduction of a foreign agent such as serum, vaccine, antigenic substance or organism. "In the delayed phase of infection (from day 8 to day 12), LIPG expression was induced more in HBV-infected cells, as previously reported." (PMID 41406170, 2025). "LIPG overexpression increased HBV attachment, uptake, and infection establishment (HBV DNA and cccDNA) in comparison to control cells." (PMID 37655967, 2023). "As expected, heparin and heparinase-reduced HBV attachment, uptake, and infection establishment in control cells and these compounds also reduced the LIPG-mediated increase of HBV attachment, uptake, and infection establishment." (PMID 37655967, 2023).
Heart Disease (2 papers, 2020 to 2025). "Since LIPG can hydrolyze HDL phospholipids, the overabundance of LIPG leads to the lower circulating levels of HDL, which promotes heart disease." (PMID 32488004, 2020).
bacterial infection (1 paper, 2008).
LIPG also shares sentences with these, for which no sentence is quoted: diabetes (4 papers); Sepsis (4); familial hypercholesterolemia (3); Cognitive impairment (2); type 1 diabetes (2); type 2 diabetes (2); Abdominal obesity (1); acute myocardial infarction (1); anemia (1); cerebrotendinous xanthomatosis (1); cervical cancer (1); clear cell renal cell carcinoma (1); colon cancer (1); coronary atherosclerosis (1); familial hypobetalipoproteinemia (1); hair disorders (1); hepatitis B virus infection (1); Hodgkin’s disease (1); Hyperglycemia (1); Hypoalbuminemia (1); lipid metabolism disorders (1); metabolic disorders (1); myopathy (1); non-alcoholic steatohepatitis (1); prostate carcinoma (1); rectum adenocarcinoma (1); respiratory diseases (1); stomach cancer (1); testicular germ cell tumor (1).